CRP (C-reactive protein)
Diseases named in the same sentence as CRP in open-access papers (continued):
Sharing a sentence is not in itself a finding about the gene and the disease.
COVID-19 (continued). "CRP during COVID-19 was significantly related to during-COVID-19 time in bed, which is expected based on the past literature highlighting the relationship between poor sleep and elevated CRP in adolescents." (PMID 38136035, 2023). "We found that EVs from COVID-19 patients carry CRP, PF4, and HMGB-1 on their surface, which may further fuel immunothrombosis." (PMID 38069209, 2023). "COVID-19-associated death was significantly associated with AEP, high LDH and CRP, age, systemic immune-inflammation biomarkers such as NLR and SII, and comorbidities, including cardiovascular diseases, lung diseases, and diabetes mellitus, and the presence of two or more comorbidities." (PMID 37766326, 2023). "Consequently, we tested the following parameters as independent predictors for PWV, AoS, AoSI, and AoD: CRP, days since COVID-19 diagnosis, the severity of the lung injury, and PCFS, as well as TyG, VAI, and LAP." (PMID 36831027, 2023). "Here we investigated the pCRP and mCRP levels within a cohort of hospitalized COVID-19 patients throughout 2020 and 2021 in Sweden, to determine if both isoforms of CRP could be useful prognostic indicators for serious disease." (PMID 37724104, 2023). "Erythrocyte sedimentation rate and C-reactive protein were elevated in 25 and 20% of patients, respectively, and could be considered as useful biomarkers for the treatment of post-COVID-19 patients." (PMID 37373960, 2023). "Comparison of patients who did and did not have significant increase in thyroid volume showed that patients with significant increase in thyroid volume had higher SARS-CoV-2 viral load in acute COVID-19 (p = 0.004), lower CRP in acute COVID-19 (p = 0.014) and less dexamethasone use (p = 0.010)." (PMID 36949763, 2023). "In patients with COVID-19, lymphopenia, thrombocytopenia, and hypoalbuminemia, and increases in D-dimer, C-Reactive Protein (CRP), creatinine, aminotransferases, cardiac troponins, total bilirubin, erythrocyte sedimentation rate, prothrombin time, and procalcitonin values come to the fore." (PMID 36826007, 2023). "In addition, C-reactive protein (CRP) was frequently found elevated in COVID-19 patients, including children with severe MIS-C." (PMID 38066446, 2023). "While baseline CRP levels are higher in women, obese individuals, and older adults, the relationship between CRP, sex, body mass index (BMI), age, and COVID-19 outcomes remains unknown." (PMID 38003780, 2023). "Therefore, the production of CRP is enhanced by both inflammatory cytokines and the degradation of tissue in COVID-19-infected patients." (PMID 36836429, 2023). "The pathogenesis of COVID-19 involves a potent inflammatory response, and CRP is an early predictor of severe COVID-19 and extremely elevated CRP levels may precede or reflect cytokine storm." (PMID 37744432, 2023). "Prolonged fever duration and higher PCR test cycle threshold values, WBC levels, and high-sensitivity C-reactive protein (hsCRP) levels may indicate bacterial coinfections in children with COVID-19." (PMID 37144031, 2023). "In addition to elevated IL-10 levels, TNF-α and IL-23 were also increased in serum of COVID-19 patients and correlated positively with CRP levels." (PMID 37283736, 2023). "C-reactive protein (CRP) and the neutrophil-to-lymphocyte ratio (NLR) are common inflammatory markers, and some reports suggest that they can be useful in predicting mortality associated with COVID-19." (PMID 37939245, 2023). "Normal levels of C-reactive protein and the lack of dimerized plasmin fragment D (D-dimer) testing were associated with hospitalizations for reasons other than COVID-19." (PMID 37621195, 2023). "We found significantly higher syndecan-1 concentrations in patients with confirmed infectious pathology (including COVID-19), but when comparing strictly to the relevant C-reactive protein (CRP), the association was no longer significant (p = 0.234)." (PMID 37109427, 2023).
COVID-19 (continued). "In addition, changes in the proteome of the extracellular vesicles of COVID-19 were also observed; in particular, the proteins CRP and Serpin A3 were also found to be increased in the patient group." (PMID 37681923, 2023). "CRP has been found to be an early indicator of the severity of COVID-19." (PMID 37390087, 2023). "The panel evaluated potential applications of CRP POC testing specifically related to COVID-19." (PMID 36673130, 2023). "This difference might imply that patients in the intervention group were suffering from a more severe disease compared to the control group, as a higher CRP could be an early sign for more severe COVID-19." (PMID 37238948, 2023). "The third major finding of this study is that the three biomarkers of Long COVID assessed in our study (CRP, KYN/TRY, and IR) or acute COVID-19 + Long COVID (CRP, KYN/TRY, IR, SpO2, and PBT) together explain a large part of the variance in the physio-affective phenome of Long COVID (around 40–41%)." (PMID 37333619, 2023). "In COVID-19 patients, ROC analysis regarding the detection of infiltrate above the median compared to infiltrate below the median showed satisfying predictive values for CRP (AUC = 0.82, p < 0.001) and IL-6 (AUC = 0.78, p < 0.001)." (PMID 37733154, 2023). "Thus, CRP should be considered a prognostic marker during the treatment of COVID-19 illness in cancer patients." (PMID 38127882, 2023). "Furthermore, the ROC analysis revealed that MDW is superior to severity, WBC count and CRP to predict COVID-19." (PMID 36973757, 2023). "Recent work examining the relationship between peak CRP and D-dimer values in hospitalized COVID-19 patients found that higher D-dimer, in combination with female sex and smoking history, was associated with reduced diffusing capacity at approximately 3-months follow up." (PMID 37391742, 2023). "In addition, according to a retrospective clinical trial, sarilumab treatment improved clinical symptoms and reduced serum CRP concentrations in most COVID-19 patients." (PMID 36793739, 2023). "Therefore, we suggest that CRP should be used to screen severe COVID-19 patients and CLR should be used to predict the prognosis of patients at the early stage." (PMID 37089472, 2023). "Our study also demonstrates significant differences in CRP in the severity of COVID-19." (PMID 37390087, 2023). "Pro-inflammatory cytokines, in particular elevated levels of C-reactive protein (CRP), D-dimer, and interleukin (IL) 1β, IL6, IL8, IL17, and tumor necrosis factor α (TNF-α), are associated with the worst outcome and high mortality in COVID-19 patients." (PMID 37534078, 2023). "In patients with COVID-19 associated CLL, abnormal D-dimer levels and antinuclear antibodies were found in 14.8% and in 11.5% while abnormalities of inflammatory parameters like ferritin, CRP or lymphocytes were found only sporadically." (PMID 37231476, 2023). "Besides IL-6, CRP and platelet and neutrophil counts also allowed to discriminate between death and discharge in patients hospitalized with severe COVID-19, but only during the first wave." (PMID 36817433, 2023). "Our results do not support a direct association between IL-6 and PCT serum levels and mortality rate in severe COVID-19 patients but suggest that CRP may be a more reliable surrogate of COVID-19 patient’s outcomes." (PMID 37109370, 2023). "The matrix showed a significant and strong positive correlation between the suPAR level and COVID-19 severity (r = 0.88) and the need for O2 therapy (r = 0.79), and a moderate positive correlation with CRP, LDH, TLC, PT, INR, and NLR (r = 0.49, 0.43, 0.43, 0.32, 0.32, and 0.31), respectively." (PMID 37108340, 2023). "Few studies have shown a curvy relationship between CRP and mortality in patients with COVID-19." (PMID 37990060, 2023).
COVID-19 (continued). "Since biochemical parameters contained in ordinary blood exams, for example, lactate dehydrogenase (LDH), C-reactive protein (CRP), etc., change over the course of the COVID-19 contamination, blood tests can provide physicians with data about the diagnosis of COVID-19." (PMID 37238232, 2023). "The increase in CRP may result from the SARS-CoV-2 virus or bacterial co-infection in severe COVID-19 cases." (PMID 36819137, 2023). "The elevated plasma concentrations of CRP and the cytokines evaluated in the present study have also been observed in other inflammatory conditions, such as rheumatoid arthritis, systemic lupus erythematosus, visceral leishmaniasis, and COVID-19." (PMID 37896187, 2023). "Through a fixed-effect analysis, the results showed that probiotics could reduce CRP serum level in patients with COVID-19 (MD = −4.03, 95% CI [−5.12, −2.93], P < 0.00001)." (PMID 37284648, 2023). "In addition, COVID-19 patients with elevated CRP levels need continual monitoring and treatment, even if they did not develop symptoms consistent with a severe disease course." (PMID 36836429, 2023). "Next, we compared the effect of inactivated COVID-19 vaccine on circulating EOS and other factors associated with the activated inflammatory response such as CRP and NLR, according to the vaccination doses, and the time from the last anti-COVID-19 vaccine dose to the symptom onset." (PMID 37217986, 2023). "CRP is also considered to be a predictor of bacterial infection in COVID-19, but its utility in predicting bacteraemia in COVID-19 is unknown." (PMID 37939245, 2023). "Hence, the present work assessed the vitamin E intake and its relationship with lipid peroxidation and C-reactive protein in patients with flu symptoms and COVID-19 diagnosis." (PMID 39263681, 2023). "Therefore, one would expect that in patients with depression and after COVID-19, persistent inflammation would be expressed by higher CRP and D-dimer parameters." (PMID 38002663, 2023). "Furthermore, due to dyslipidemia, there is an increase in triglycerides, free fatty acids, inflammatory cytokines, insulin resistance, and C-reactive protein (CRP), which increase the risk of severe COVID-19 cases and mortality." (PMID 37888519, 2023). "This implies that ADHD-related increases in systemic CRP concentrations may play a role in pulmonary fibrosis in COVID-19." (PMID 38066446, 2023). "Serum ferritin, C-reactive protein (CRP), D-dimer, and interleukin-6 (IL-6) are examples of inflammatory markers that have been shown to be strongly linked to the high risks of developing severe COVID-19." (PMID 37575788, 2023). "Similar studies on predictors of COVID-19 severity have also been performed in other countries, in which CRP, LDH, neutrophil-to-lymphocyte ratio, age, lymphocyte count, and malignancy were found to be associated with intubation using chi-square automatic interaction detection analysis." (PMID 37720137, 2023). "Severe COVID-19 is classically associated with elevated values of systemic non-specific inflammatory biomarkers including CRP, ferritin and D-dimers." (PMID 37189619, 2023). "In addition to elevated systemic cytokine levels and activated immune cells, several clinical and laboratory abnormalities, such as elevated CRP and d-dimer levels, hypoalbuminemia, renal dysfunction, and effusions, are also observed in COVID-19." (PMID 38007416, 2023). "As for the secondary clinical endpoint (CRP), which indicates the inflammatory status of the body, the treatment group demonstrated a more rapid normalization of the elevated CRP levels, which favors a low incidence of COVID-19 complications." (PMID 37375747, 2023). "Moreover, in this study, the clinical investigation in patients with diabetes and severe COVID-19 presented higher serum concentrations of CRP and LDH." (PMID 38248722, 2023). "Well-known early markers ofinflammation or infection CRP may be useful for early detection of severity during COVID-19." (PMID 37790205, 2023).
COVID-19 (continued). "Specifically, CRP levels have been shown to be correlated with adverse COVID-19 outcomes." (PMID 38051999, 2023). "The value of CRP was significantly higher in the COVID-19 group than the control group." (PMID 37834884, 2023). "The high risks of developing severe COVID-19 are strongly associated with inflammatory markers such as procalcitonin (PCT), serum ferritin, erythrocyte sedimentation rate (ESR), C-reactive protein (CRP), and interleukin-6 (IL-6)." (PMID 36837428, 2023). "Therefore, CRP is considered the most effective and sensitive biomarker for predicting the progression of COVID-19." (PMID 38248722, 2023). "Age and CRP were much higher in the severe and critical groups of COVID-19 than in the mild group." (PMID 36999046, 2023). "C-reactive protein and lymphocytes both are routinely studied in most patients with COVID-19." (PMID 37653759, 2023). "Notably, DM and Non-DM patients presented neutrophil-to-lymphocyte ratio, lymphocyte, neutrophil, monocyte count, AST, ALT, c-reactive protein, activated partial thromboplastin time and platelets returned to within reference ranges post-COVID-19." (PMID 36045733, 2022). "Although with a very high heterogeneity, in general, the existing literature demonstrates the prognostic capacity of CRP/SA ratio in the hospitalized COVID-19 patient, as well as that this predictive capacity is higher than that of each one of the parameters alone." (PMID 35740416, 2022). "The prognostic role of D-Dimer, C-reactive protein (CRP), and fibrinogen levels in the incidence of thromboembolic events and mortality in COVID-19 patients is well-known and has been extensively researched in the specialized literature over the last two years." (PMID 36428817, 2022). "The results showed that increased CRP (>4 mg/L) (OR = 11.438, 95% CI: 1.607-81.416, p = 0.015) and higher LDH (>243 IU/L) (OR = 7.631, 95% CI: 1.123-51.880, p = 0.038) were associated with increased risk factors for severe events in all COVID-19 patients." (PMID 36033814, 2022). "In addition to delirium, only three other factors were identified as predictors of death in COVID-19 patients by our multivariable model: comorbidity measured with the Charlson Index, CRP, and NLR." (PMID 35204633, 2022). "In a cohort of COVID-19 patients, the levels of ALAT/ASAT elevation detected in the study were mild and more commonly associated with higher inflammatory indices, such as elevated C-reactive protein (CRP) and procalcitonin (PCT)." (PMID 35425729, 2022). "However, multiple studies have shown differences in cellular immune responses, COVID-19 specific antibody levels, and many commonly measured inflammatory markers in clinical practice (e.g. C-reactive protein)." (PMID 36171541, 2022). "Therefore, we aimed to determine the potential of monomeric CRP in serum as a biomarker of disease severity in COVID-19 patients (admission to intensive care unit [ICU] and/or in-hospital mortality)." (PMID 36741367, 2022). "In addition to the triad neutrophilia-lymphopenia-thrombocytopenia and increased concentrations of CRP, D dimer, and procalcitonin, myoglobin was found to be elevated in patients with severe COVID-19, which correlates with a hypoxemic state." (PMID 36016660, 2022). "In general, confirmed COVID-19 patients have higher CRP, D-dimer, fibrinogen, and leukocyte values." (PMID 34812130, 2022). "IL-6 ≥ 74.98 pg/mL, CRP values ≥ 81 mg/L, procalcitonin ≥ 0.56 ng/mL, and D-dimer ≥ 760 ng/mL could effectively predict in-hospital mortality in COVID-19 patients." (PMID 35237386, 2022). "A recent report of dialysis patients with COVID-19 in Japan revealed that older age (> 70 years), higher BMI, higher CRP level, and lower serum albumin levels, were aggravating factors of mortality, and that the use of remdesivir was predictive of improved mortality." (PMID 36101873, 2022).
COVID-19 (continued). "Baseline co-morbidities, specific in-hospital medications, and characteristics commonly used to define severe COVID-19 (age, severe hypotension, lymphocyte count, estimated glomerular filtration rate [eGFR], CRP, and PaO2/FIO2 ratio) were well balanced among different BP-lowering drug users." (PMID 35050225, 2022). "Since both stroke and COVID-19 lead to increases in circulating IL-6 and CRP, their combination could significantly exacerbate inflammatory mediator concentration and worsen overall patient outcome." (PMID 38566903, 2022). "We previously underlined the concept that few parameters (neutrophils, lymphocytes, CRP, LD) could be used to assess the presence and even the severity of COVID-19 during triage in the emergency room." (PMID 35464745, 2022). "Based on our study, NLR can be used as an early warning signal for severe COVID-19 disease, however further studies are required to validate this finding and it had a significant correlation with other inflammatory markers of COVID-19 severity like CRP, D-dimer, and serum ferritin." (PMID 35519791, 2022). "Patients with severe acute COVID-19 especially had elevated CRP in EVs." (PMID 35929616, 2022). "Based on these findings, we hypothesized that platelet-to-CRP ratio (PC ratio) could act as a package solution in predicting COVID-19 progression and multi-organ injuries." (PMID 35592303, 2022). "The severity of the illness and the levels of serum cardiac biomarkers (CK, CK-BM, cTnI), as well as the inflammation markers (IL-1, IL-6, CRP), were lesser in hypertensive COVID-19 patients treated with AT1R blockers than those treated with other antihypertensive drugs." (PMID 34973134, 2022). "Moreover, positive C-reactive protein (CRP) was significantly more prevalent in COVID-19 outpatients than in controls (p = 0.042)." (PMID 35453291, 2022). "Besides suPAR, LDH, CRP, neutrophil count, neutrophil-to-monocyte and neutrophil-to-lymphocyte ratio, body mass index and chronic renal failure were discriminators of COVID-19 severity and/or predictors of length of hospitalization." (PMID 36556207, 2022). "Some biomarkers to monitor disease state assess severity of COVID-19 patients have been identified including IL-6, C-reactive protein (CRP), alanine aminotransferase (ALT), aspartate aminotransferase (AST), plasma D-dimers as well as leukocyte and lymphocyte counts." (PMID 35064792, 2022). "Moreover, KL-6 has been positively correlated with CRP and IL-6 levels in patients with a severe course of COVID-19." (PMID 36362828, 2022). "An initial simple multiple biomarker strategy comprised of CRP, D-dimer and hs-TnI demonstrated promising results for estimating the risk of death and ICU admission in patients hospitalized with COVID-19, although the influence of underlying age differences cannot be excluded." (PMID 35176874, 2022). "ROC curve analysis revealed that the combination of SAA and CRP was valuable in evaluating the disease progression and prognosis of COVID-19 patients at different time points; however, a combination of SAA and lymphocyte counts was more sensitive for disease severity prediction on admission." (PMID 36465717, 2022). "Our findings, that approximately one-third of patients hospitalized with COVID-19 had abnormal X-ray findings and WBCs counts, with 17.1% manifesting out of range of CRP levels, is similar to a study from Jordan regarding abnormal X-ray findings and China regarding WBCs." (PMID 35740195, 2022). "Increased age, the involvement of two or more comorbidities, deranged hematological parameters, elevated CRP, PCT, NLR, D-dimer, LDH levels, irregular CT-scan results, and palliative therapy are all linked to the deteriorating condition in COVID-19 patients, potentially increasing the risk of death." (PMID 35127069, 2022).